RNU6-163P (RNA, U6 small nuclear 163, pseudogene)
Gene: Small nuclear RNA gene on chromosome 10 (4,514,952 to 4,515,057, forward strand). Ensembl gene ENSG00000207124.
Homologues: Orthologues: chimpanzee U6 (100% identical), macaque U6 (90% identical), pig U6 (75% identical), guinea pig U6 (73% identical). Paralogues in human: RNU6-166P (84% identical), RNU6-41P (84% identical), RNU6-517P (84% identical), RNU6-842P (84% identical), RNU6-1011P (83% identical), RNU6-1060P (83% identical), RNU6-116P (83% identical), RNU6-15P (83% identical), RNU6-22P (83% identical), RNU6-31P (83% identical), RNU6-439P (83% identical), RNU6-589P (83% identical), and 1287 more.